YTHDC1 (YTH N6-methyladenosine RNA binding protein C1)
Diseases named in the same sentence as YTHDC1 in open-access papers (continued):
Sharing a sentence is not in itself a finding about the gene and the disease.
ischemic stroke (9 papers, 2020 to 2025). A stroke disorder caused by obstruction of blood flow to the brain, due to thrombotic (local blood clot formation) or embolic (due to a blood clot or other material traveling from another site) event. "METTL3 and YTHDC1 promote Akt phosphorylation to alleviate ischemic stroke by destabilizing PTEN mRNA." (PMID 38180752, 2024). "Overexpression of YTHDC1 reversed these effects, confirming the protective effect of YTHDC1 on ischemic stroke-induced neuronal apoptosis." (PMID 36246528, 2022). "Our data elucidate a new role of YTHDC1 in brain injury and indicate the potential involvement of m6A modification in the regulation of ischemic stroke." (PMID 33188203, 2020). "Targeting YTHDC1 provides a potential therapeutic strategy for reducing cerebral I/R injury, although the function of other m6A writers, readers, and erasers in ischemic stroke still await further investigation." (PMID 33188203, 2020). "It was observed that YTHDC1 could be protective against ischemic stroke by enhancing Akt phosphorylation via destabilizing PTEN mRNA." (PMID 37528851, 2023). "In a rat cerebral ischemia model, YTHDC1 was up-regulated in the early phase of ischemic stroke." (PMID 36246528, 2022). "In this study, we found that YTHDC1 was unregulated in the early phase of ischemic stroke." (PMID 33188203, 2020). "Here, we found that YTHDC1 was unregulated in the early phase of ischemic stroke." (PMID 33188203, 2020). "Furthermore, in a rat ischemic stroke model, overexpression of m6A reader YTHDC1 alleviated brain neurological deficits as measured by NSS through promoting phosphatase and tensin homolog (PTEN) mRNA degradation to increase protein kinase B (AKT) phosphorylation." (PMID 36246528, 2022). "The role of YTHDC1 in neuronal survival and ischemic stroke is unknown." (PMID 33188203, 2020). "YTHDC1 disrupts the stability of PTEN mRNA and activates Akt phosphorylation to alleviate ischemic stroke induced neurological injury." (PMID 38978074, 2024). "Facing the enhanced PTEN expression induced by m6A modification in cancers, expression of YTHDC1 (YTH domain containing 1), one of the ‘readers’, discriminately destabilized PTEN mRNA which was discovered to mediate neuronal survival and ischemic stroke." (PMID 37070134, 2023). "YTHDC1 promotes AKT phosphorylation by degrading PTEN mRNA, thereby alleviating ischemic stroke." (PMID 40180937, 2025). "Mechanistically, YTHDC1 promoted PTEN mRNA degradation to increase AKT phosphorylation, thus up-regulating the expression of Bcl-2, down-regulating the expression of cleaved caspase-3 and facilitating neuronal survival after ischemic stroke." (PMID 36246528, 2022). "Moreover, YTHDC1, a m6A reader, promoted PTEN mRNA degradation to increase AKT phosphorylation, thus facilitating neuronal survival in ischemic stroke." (PMID 36246528, 2022). "So far, the role of YTHDC1 in cell survival and ischemic stroke is not understood." (PMID 33188203, 2020).
osteosarcoma (9 papers, 2021 to 2025). A usually aggressive malignant bone-forming mesenchymal neoplasm, predominantly affecting adolescents and young adults. "RBM15 and YTHDC1 can serve as potential prognostic biomarkers associated with m6A in osteosarcoma." (PMID 37002245, 2023). "Molecular therapy targeting NAT10 and YTHDC1 has shown potential for the treatment of various diseases, including osteosarcoma." (PMID 38233839, 2024). "Despite these challenges, targeting NAT10 and YTHDC1 remains a promising therapeutic strategy for various diseases, including osteosarcoma." (PMID 38233839, 2024). "Overall, our study sheds new light on the regulation of glycolysis in osteosarcoma by YTHDC1 and provides a promising therapeutic target for this disease." (PMID 38233839, 2024). "Our article shows that YTHDC1 transcript was a critical target gene for ac4C acetylation, while indeed affects glycolysis in osteosarcoma cells by examining differences in glucose, lactate, and pyruvate content in cells or media after NAT10 knockdown." (PMID 38233839, 2024). "The positive rate of specific staining for YTHDC1 was higher in osteosarcoma than in paraneoplastic tissues, and the difference was statistically significant (P < 0.05)." (PMID 37002245, 2023). "The positive area of specific staining expression of YTHDC1 was significantly more abundant in osteosarcoma than in paraneoplastic tissues (Fig. 11C1–D2)." (PMID 37002245, 2023). "Based on two large-scale cohorts, HNRNPA2B1, HNRNPC, RBM15, YTHDF1, and YTHDC1 expression levels are upregulated in osteosarcoma tissues." (PMID 34094986, 2021). "Through analyzing the prognosis information of osteosarcoma patients, METTL3, YTHDC1, and FTO were identified as significant markers associated with OS probability." (PMID 34011074, 2021). "Multivariate Cox-regression analysis identified METTL3, YTHDC1, and FTO as significant osteosarcoma OS probability-associated markers in training set." (PMID 34011074, 2021). "However, in our study, we found that YTHDC1-mediated regulation of nuclear RNA is critical for osteosarcoma development." (PMID 38233839, 2024). "Therefore, our findings suggest that NAT10 serves as an effective and novel therapeutic target for osteosarcoma through YTHDC1-mediated m6A modification, which can impact the translation efficiency of LDHA and PFKM." (PMID 38233839, 2024). "In addition, we found that knocking down YTHDC1 inhibited osteosarcoma cells growth, proliferation and migration as compared with siNC group in U2OS and 143B cells." (PMID 38233839, 2024). "Furthermore, lentiviral depleting NAT10 remarkably inhibited the colony-formation capacity in both U2OS and 143B osteosarcoma cells in colony-formation assays, lentiviral overexpression of YTHDC1 significantly abolished this effect." (PMID 38233839, 2024). "Additionally, our study is the first to reveal that NAT10-mediated YTHDC1 mRNA decay is partially due to the reduced stability of its mRNA transcript, leading to the inhibition of protein translation and suppressing osteosarcoma cell growth." (PMID 38233839, 2024). "miR-451a promoted cell growth, migration, and EMT in osteosarcoma and activated the AKT/mTOR signalling pathway via YTHDC1-mediated m6A methylation." (PMID 38943031, 2024). "ac4C‐modified YTHDC1 mediates m6A methylation of PFKM and LDHA to regulate glucose metabolism and promote progression of osteosarcoma." (PMID 39640362, 2024). "YTHDC1 recognizes differential m6A sites on PFKM and LDHA RNAs, which promotes osteosarcoma cell growth and regulates glycolysis pathway by increasing PFKM and LDHA mRNA stability in an m6A methylation-dependent manner." (PMID 38233839, 2024). "METTL3, YTHDC1, and FTO were identified as key regulators, and the osteosarcoma prognostic signature based on these m6A regulator could prognostically stratify the patients independently of potential confounding factors." (PMID 34011074, 2021).
osteosarcoma (continued). "To our knowledge, we are the first to report that osteosarcoma patients could be prognostically stratified using METTL3, YTHDC1, and FTO, which is independent of potential confounding factors including age, gender, and metastatic status." (PMID 34011074, 2021).
pancreatic cancer (9 papers, 2021 to 2024). "ZC3H13 (11%), RBM15B (9%), YTHDF1 (8%), and YTHDC1 (6%) frequently occurred genetic mutations in pancreatic cancer." (PMID 34603372, 2021). "YTHDC1 can target miR-30d, a tumor suppressor gene that modifies pancreatic cancer, which in turn inhibits glycolysis and controls the development of pancreatic cancer." (PMID 39033180, 2024). "In pancreatic cancer, YTHDC1 hypermutation suggests a poor outcome in pancreatic cancer." (PMID 38600232, 2024). "YTHDC1 inhibits the glycolytic process through the miR-30d/RUNX1 axis in pancreatic cancer cells." (PMID 37258572, 2023). "Moreover, YTHDC1 was also found to inhibit glycolysis in pancreatic cancer through the miR-30d/RUNX1 axis." (PMID 35974388, 2022). "Furthermore, pancreatic cancer patients with lower METTL3, METTL14, RBMX, FTO, ALKBH5, YTHDF1, and YTHDC1 mRNA expression levels or higher VIRMA, HNRNPA2B1, EIF3A, IGF2BP1, IGF2BP2, and IGF2BP3 mRNA expression levels had significantly poorer OS (P < 0.05)." (PMID 34330301, 2021).
glioblastoma (7 papers, 2020 to 2025). The most malignant astrocytic tumor (WHO grade IV). "YTHDC1, identified as a crucial factor in glioblastoma, can modulate glioblastoma development through interactions with specific mRNA molecules." (PMID 39342406, 2024). "YTHDC1 also participates in the tumorigenesis of glioblastoma by reading the m6A marks dependent on its tryptophan 377 (W377) or W428 sites." (PMID 35625706, 2022). "YTHDC1 has been shown to promote m6A/METTL3-mediated tumor cell growth in glioblastoma (GBM) via regulation of nonsense-mediated mRNA decay (NMD) of serine- and arginine-rich splicing factors (SRSF)." (PMID 33922187, 2021). "We used the TCGA microarray database and compared the mRNA expression levels of five YTH domain family proteins, YTHDF1, YTHDF2, YTHDF3, YTHDC1, and YTHDC2, between 720 normal brain tissue microarray datasets and 582 glioblastoma datasets." (PMID 33317545, 2020). "The downregulation of METTL3 in glioblastoma cells (GBM) decreased the m6A modification levels of serine- and arginine-rich splicing factors (SRSF), which led to the YTHDC1-dependent nonsense-mediated decay (NMD) of SRSF transcripts and decreased SRSF protein expression." (PMID 36835633, 2023). "Overexpression of YTHDC1 W377A/W428A mutant also failed to enhance sphere formation of U87 cells, suggesting that YTFDC1 contributes to the glioblastoma phenotype dependent on its m6A-binding activity." (PMID 35625706, 2022).
endometrial cancer (6 papers, 2018 to 2022). Primary or metastatic malignant neoplasm involving the endometrium (mucous membrane that lines the endometrial cavity). "YTHDC1 and METTL14, in particular, have been identified as possible endometrial carcinoma diagnostic and prognostic indicators." (PMID 35159736, 2022). "Meanwhile, ZC3H13 or YTHDC1 knockdown promoted the proliferation and invasion of endometrial cancer cells." (PMID 34230220, 2021). "To investigate the carcinogenic effect of ZC3H13 and YTHDC1 in endometrial carcinoma, we knocked them down in Ishikawa and HEC-1A cell lines." (PMID 34230220, 2021). "In addition, some studies also reported that that YTHDC1 interacted with other splicing factors and could be used as potential tumor suppressors for endometrial cancer." (PMID 34897032, 2021). "In particular, ZC3H13, YTHDC1, and METTL14 were identified as potential markers for endometrial cancer diagnosis and prognosis." (PMID 34230220, 2021).
melanoma (6 papers, 2020 to 2026). A malignant, usually aggressive tumor composed of atypical, neoplastic melanocytes. "In GEO datasets, except YTHDC2, other m6A readers like YTHDF1, YTHDF2, YTHDF3 and YTHDC1 have a significant higher expression in melanoma tissues." (PMID 36324258, 2022). "Additionally, western blot analysis revealed that the expression of three vital proteins that regulate m6A modification, namely METTL3, YTHDF2, and YTHDC1, was reduced in melanoma cells after DHPS knockdown." (PMID 38952061, 2024). "We discovered that N6-methyladenosine (m6A) modulators-specifically YTHDF3, YTHDC1, and METTL14-cooperatively upregulate BGN expression in a parallel, non-hierarchical manner converging on functional m6A sites within melanoma cells." (PMID 41833003, 2026). "Comparing primary melanoma and metastases, we found that ALKBH5, ELAVL1, FMR1, HNRNPA2B1, HNRNPC, IGF2BP1/2/3, KIAA1429, LRPPRC, RBM15, YTHDC1/2, YTHDF1/3, and ZC3H13 were significantly upregulated in metastases, while RBM15B and METTL3 were significantly upregulated in primary melanoma." (PMID 34993195, 2021). "Subsequent studies revealed that METTL3 could not regulate the expression of YTHDC1/YTHDF2 proteins in melanoma, which also predicts that the methylation modifications regulated by METTL3 are not required for all genes, but that METTL3‐mediated m6A‐methylation modification is dependent on DHPS." (PMID 38952061, 2024).
pulmonary fibrosis (6 papers, 2022 to 2025). Chronic progressive interstitial lung disorder characterized by the replacement of the lung tissue by connective tissue, leading to progressive dyspnea, respiratory failure, or right heart failure. "This study first clarified that YTHDC1 phase separation is crucial for the m6A modification, nuclear export, and profibrotic role of lnc668 in exacerbating pulmonary fibrosis." (PMID 40221424, 2025). "Studies have shown that YTHDC1 expression is reduced in both IPF patients and mouse models of pulmonary fibrosis, whereas YTHDC1 overexpression inhibits senescence and mitigates IPF in vitro and in vivo." (PMID 40230412, 2025). "In this study, we focused on how phase-separating YTHDC1 promotes the nuclear export of lnc668 to accelerate fibroblast-to-myofibroblast differentiation, resulting in pulmonary fibrosis." (PMID 40221424, 2025). "Researchers found that a protein called YTHDC1 can delay cellular senescence and reduce lung fibrosis by improving DNA repair in cells." (PMID 40634753, 2025). "After nuclear export, lnc668 facilitated the translation and stability of its host gene PICALM to activate fibroblast-to-myofibroblast differentiation, leading to the aggravation of pulmonary fibrosis, which also depended on the phase separation of YTHDC1." (PMID 40221424, 2025). "Excitingly, the results revealed that overexpression of YTHDC1 prevents senescence both in vivo and in vitro, and further antagonizes pulmonary fibrosis." (PMID 38177310, 2024). "The reduction of YTHDC1 probably leads to pulmonary fibrosis progress, as we observed that knockdown of YTHDC1 exacerbates stress-induced senescence and pulmonary fibrosis." (PMID 38177310, 2024). "Here, the RNA-binding protein YTHDC1 is identified as antagonist of idiopathic pulmonary fibrosis (IPF), acting independently of its m6A-reader function by activating DNA damage effector ATR." (PMID 38177310, 2024). "Altogether, these results display that depletion of YTHDC1 promotes stress-induced senescence and lung fibrosis, supporting the idea that YTHDC1 plays a protective role during pulmonary senescence and fibrosis progress." (PMID 38177310, 2024). "After nuclear export, lnc668 facilitated the translation and stability of its host gene phosphatidylinositol-binding clathrin assembly protein to activate fibroblast-to-myofibroblast differentiation, leading to the aggravation of pulmonary fibrosis, which also depended on YTHDC1 phase separation." (PMID 40221424, 2025). "Recently, it was shown that YTHDC1 was downregulated in pulmonary fibrosis in ATII cells." (PMID 40634753, 2025). "The coming question is whether the effects of YTHDC1 on stress-induced senescence and pulmonary fibrosis depends on the activation of ATR." (PMID 38177310, 2024). "We also overexpressed wild type or mutant YTHDC1 in pulmonary fibrosis mice model using AAV system." (PMID 38177310, 2024). "In spite of this, these results still indicate YTHDC1 is an important regulator in senescence and provides a potential therapeutic target in reversing cellular senescence and treating age-related disorders such as pulmonary fibrosis." (PMID 38177310, 2024). "Then, we studied the effect of YTHDC1 depletion on senescence and lung fibrosis in mice." (PMID 38177310, 2024). "However, whether lncRNA nuclear export depends on YTHDC1 phase separation and whether phase separation directly affects the occurrence and development of pulmonary fibrosis remain unproven." (PMID 40221424, 2025). "We focused on the role of YTHDC1 in stress-induced AECII senescence and bleomycin-induced mouse pulmonary fibrosis." (PMID 38177310, 2024). "Strikingly, YTHDC1 primarily expresses in AECII (SPC positive) cells in normal lung tissues and significantly decreases during lung fibrosis." (PMID 38177310, 2024). "We observed reduced YTHDC1 expression in both IPF patients and pulmonary fibrosis mice model." (PMID 38177310, 2024).
pulmonary fibrosis (continued). "Hence, it is possible that decreased expression of YTHDC1 impairs ATR activation and DNA damage repair, leading to cellular senescence and diseases, such as idiopathic pulmonary fibrosis." (PMID 38177310, 2024). "Although we observed the anti-aging function of YTHDC1 in AECII, we cannot rule out the effect of YTHDC1 on other lung cell types in lung fibrosis." (PMID 38177310, 2024).
cervical cancer (5 papers, 2022). A primary or metastatic malignant neoplasm involving the cervix. "ZC3H13 and YTHDC1 could act as an prognostic indicator in cervical cancer." (PMID 36072430, 2022). "Through further GO and KEGG clustering analysis of the functions of these three factors (YTHDC1, YTHDC2 and RBM15), we infer that ERBB3 methylation plays an important role in the occurrence and progression of cervical cancer." (PMID 35581263, 2022). "We revealed higher levels of ZC3H13, WTAP, HNRNPC, YTHDF3, and VIRMA were significantly associated with worse outcomes in CESC (HR > 1, blue background), while YTHDC1, YTHDF1 were protective factors of cervical cancer (HR < 1, orange background)." (PMID 35581263, 2022). "Differential analysis results showed that many m6A-related genes were differentially expressed between cervical cancer tissues and normal tissues, including METTL14, METTL16, ZC3H13, YTHDC1, and YTHDC2." (PMID 36058934, 2022). "YTHDC1 and YTHDF1 have anti-cancer effects in cervical cancer, while ZC3H13, WTAP, HNRNPC, YTHDF3 and VIRMA have tumor-promoting effects in cervical cancer." (PMID 35581263, 2022). "We speculated that low expressed TRPV1 promotes cervical cancer tumorigenesis through YTHDF1/2/3, HNRNPA2B1, YTHDC1/2, ZC3H13, and METTL14 modification." (PMID 36072430, 2022).
hepatoblastoma (5 papers, 2021 to 2023). Hepatoblastoma (HB) is a malignant hepatic tumor and is the most common pediatric liver cancer. "YTHDC1 rs3813832 TC genotype significantly reduced the susceptibility of neuroblastoma, and rs2293596 T>C polymorphism might contribute to hepatoblastoma susceptibly." (PMID 36072379, 2022). "More recently, our group found that YTHDC1 rs2293596 T>C polymorphism predisposed to hepatoblastoma and YTHDC1 gene polymorphisms may have a cumulative effect on hepatoblastoma risk." (PMID 34897032, 2021). "We have previously shown that several RNA m6A-mediated genes (i.e., METTL3, METTL14, WTAP, YTHD1, YTHDC1, and ALKBH5) are associated with hepatoblastoma susceptibility." (PMID 35986847, 2022). "Our group has previously reported that many genetic variants of genes encoding RNA m6A and m7G methyltransferase, demethylase, and m6A-reading proteins confer hepatoblastoma susceptibility, including METTL3, METTL4, AlkB homolog 5 (ALKBH5), FTO, YTHDC1, YTHDF1, WTAP, WDR4, and METTL1." (PMID 37531210, 2023). "Similar studies detected the association between YTHDC1 and ALKBH5 polymorphism and hepatoblastoma." (PMID 34367972, 2021).